GDF15 (growth differentiation factor 15)
Diseases named in the same sentence as GDF15 in open-access papers (continued):
Sharing a sentence is not in itself a finding about the gene and the disease.
neuropathy (6 papers, 2022 to 2026). A disorder affecting the nervous system that manifests with pain, tingling, numbness, and/or muscle weakness. "To verify the serum GDF15 prediction model with conventional neuropathy risk factors, we evaluated the different AUC estimates among these factors." (PMID 35683420, 2022). "This study showed that the GDF-15 concentrations were approximately 20% higher in the T1D group compared to healthy controls, and that subgroups with complications (albuminuria and neuropathy) had the highest concentrations." (PMID 39000435, 2024). "NIA was correlated with GDF-15 in the merged T1D group, as well as in the subgroups divided based on neuropathy." (PMID 39000435, 2024). "GDF15 was significantly elevated in CMT in comparison to the non-neuropathy disease controls GNE myopathy and BMD/DMD." (PMID 35148379, 2022). "Recently, GDF-15 has also been reported to be a predictive marker of neuropathy in T2D." (PMID 39000435, 2024). "Our data indicate that serum GDF15 is a highly selective diagnostic biomarker of CMT (AUC of 0.972, 95% CI; 0.936–1), while NCAM1 (AUC 0.748, 95% CI; 0.6268–0.869) is a more suitable serum biomarker of neuropathy progression." (PMID 35148379, 2022). "The GDF-15 concentration was higher in the group with neuropathy, 459.3 (428.2), as compared to the group without neuropathy, 325.2 (103.9) pg/mL (p = 0.009)." (PMID 39000435, 2024). "GDF-15 was correlated with age only in the group without neuropathy." (PMID 39000435, 2024). "Unlike NCAM1, GDF15 was greatly increased even in mildly affected CMT patients and increased prior to neuropathy onset in the axonal Hsbp8K141N mouse model." (PMID 35148379, 2022). "Furthermore, correlations of GDF-15 and hs-CRP were found in the whole T1D group, but not in any neuropathy subgroup." (PMID 39000435, 2024).
osteosarcoma (6 papers, 2020 to 2024). A usually aggressive malignant bone-forming mesenchymal neoplasm, predominantly affecting adolescents and young adults. "GDF15 may promote osteosarcoma cell metastasis by regulating the TGF-β signaling pathway, associated with poor prognosis and serving as a potential prognostic and lung metastasis-predictive biomarker." (PMID 39469643, 2024). "In addition, GDF-15 was found to promote cell migration and invasion in osteosarcoma cell lines by sustaining the TGFβ pathway." (PMID 39283723, 2024). "The expression of this cytokine was found to be upregulated in metastatic compared with nonmetastatic osteosarcoma and patients with high serum GDF-15 levels exhibited a decreased survival." (PMID 39283723, 2024).
periodontitis (6 papers, 2021 to 2025). An acute or chronic inflammatory process that affects the tissues that surround and support the teeth. "This study indicates a pro-inflammatory role of GDF15 in pathogenic and mechanical stimuli of human periodontal ligament fibroblasts associated with periodontitis and orthodontic tooth movement." (PMID 34948405, 2021). "In this regard, it has been demonstrated that during the active phases of periodontitis, bacterial LPS have been proven to stimulate elevated serum GDF-15 levels via a process involving the synthesis of proteolysis products in gingival fibroblast." (PMID 37605193, 2023). "In periodontitis patients, previous reports have shown that upregulated GDF-15 levels sustain the inflammatory response of periodontal ligament fibroblasts against P. gingivalis and orchestrate the extent of periodontal tissue destruction already in the early stage of the disease." (PMID 37605193, 2023). "Similarly, further investigations in a rat model of periodontitis showed that higher levels of serum GDF-15 were tightly correlated with the periodontal inflamed surface area already from the earliest stages of the disease." (PMID 37605193, 2023). "In this regard, several studies evidenced that, during periodontitis, imbalanced serum GDF-15 levels may influence the innate host defences against periodontal pathogens." (PMID 37605193, 2023). "In this regard, the present study has achieved significant results with Q-SRP approach with a positive correlation between serum GDF-15, GPx-1, hs-CRP and SP-D with the extent of periodontitis, evaluated through the association with the several periodontal parameters examined." (PMID 37605193, 2023). "To further characterize the periodontitis status, we analyzed the serum high-sensitivity C-reactive protein (hs-CRP) and growth differentiation factor-15 (GDF15) levels." (PMID 40351551, 2025). "In this study, NSPT significantly decreased serum GDF-15, hs-CRP, and SP-D and increased GPx-1 in patients with periodontitis." (PMID 37605193, 2023). "On the contrary, GDF15, SCD and TFAP2A had lower sensitivity in predicting periodontitis with T2DM, with AUCs of 0.54, 0.60 and 0.66, respectively." (PMID 36248844, 2022). "Recently, elevated levels of growth differentiation factor 15 (GDF15), an immuno-modulatory member of the transforming growth factor (TGFB) superfamily, were detected under periodontitis-like conditions and in force-stressed PdL cells." (PMID 34948405, 2021). "The relevant genes that were involved in the PI3K/AKT pathway activation observed in the T2DM-related periodontitis included those that affect apoptosis (e.g., FOXO1, BCL2, and growth differentiation factor 15 [GDF15]) and cell cycle passage (e.g., CDKN1B and CCND1)." (PMID 38241313, 2024). "In this regard, the purpose of the present randomized clinical trial (RCT) was to evaluate the effect of NSPT performed either through Q-SRP or FMD on GDF-15, GPx-1, hs-CRP, and SP-D concentrations in patients with periodontitis at 6-month follow-up after treatment." (PMID 37605193, 2023). "Out of the 20 most upregulated genes in periodontitis tissues compared to controls, five were induced in DAC-treated GFs in our experiments (CSF3, GLDC, SAA1, SAA2, GDF15), highlighting the notion that DNMT inhibitors upregulate several genes that are associated with periodontitis pathology." (PMID 36776856, 2023). "However, periodontal treatment performed with Q-SRP determined a better decrease in clinical periodontal parameters and improved GDF-15, GPx-1, hs-CRP and SP-D in patients with periodontitis." (PMID 37605193, 2023).
prediabetes (6 papers, 2016 to 2025). "Previous studies on the association between GDF-15 and prediabetes are very few." (PMID 27642607, 2016). "Our results suggest that increased GDF-15, as an anti-inflammatory peptide, may have a compensatory role in prediabetes, even in the early stages of subclinical inflammation." (PMID 27642607, 2016). "In patients with prediabetes, the number of senescent CD8+ T cells was positively related to serum levels of GDF-15, implying that increased GDF-15 may accelerate CD8+ T cells aging and further reduce number of CD8+ T cells." (PMID 35911685, 2022). "In addition, we analyzed the correlation between serum GDF15 level and senescent CD4+ or CD8+ T-cell numbers in the patients with prediabetes." (PMID 30867412, 2019).
thrombosis (6 papers, 2015 to 2026). "Taken together, the GDF15 level is linked and correlated with the progression of diabetic complications including thrombosis, DN, diabetic neuropathy, and DR." (PMID 36444166, 2022). "In addition, the GDF15 level is linked and correlated with the progression of diabetic complications including thrombosis, DN, diabetic neuropathy, and DR." (PMID 36444166, 2022). "On the other hand, GDF-15 might help to identify patients at high risk of thrombosis who may benefit from additional antithrombotic therapy, i.e., a PAR-1 antagonist." (PMID 35455481, 2022). "Therefore, thrombosis in T2DM could be due to elevation of GDF15, which is associated with the risk of thrombosis." (PMID 36444166, 2022). "GDF15 levels correlated positively with VWT, and increased portal VWT was independently associated with thrombosis." (PMID 40910463, 2026). "As the number of patients was low, no analysis was performed according to the thrombosis/hemorrhage history and hepcidin, GDF15, and mitoferrin-1 levels (the number of patients with a history of thrombosis and hemorrhage was 3 and 1, respectively)." (PMID 30761871, 2019). "In addition, consistent with the clinical data in Part I, serum levels of GDF15 in the mouse model of deep vein thrombosis were significantly higher than those in the control group." (PMID 37723495, 2023).
acute respiratory distress syndrome (5 papers, 2013 to 2023). Progressive and life-threatening pulmonary distress in the absence of an underlying pulmonary condition, usually following major trauma or surgery. "In cardiovascular disease and pulmonary vascular disorders, elevated circulating levels of GDF-15 have been associated with mortality, while in acute respiratory distress syndrome (ARDS), GDF-15 has been associated with several secondary outcomes." (PMID 34829345, 2021). "Furthermore, the GDF15 level positively indicates a poor prognosis in patients with acute respiratory distress syndrome." (PMID 38111379, 2023). "We sought to determine whether higher levels of the novel biomarker growth differentiation factor-15 (GDF-15) are associated with poor outcomes and the presence of pulmonary vascular dysfunction (PVD) in patients with acute respiratory distress syndrome (ARDS)." (PMID 23706007, 2013). "The concept that circulating GDF-15 reflects illness severity is supported by our observation that patients’ plasma GDF-15 correlated with their SOFA score and prior observations that elevated GDF-15 in patients with acute respiratory distress syndrome predicted poor outcome." (PMID 25516419, 2015).
AIDS (5 papers, 2020 to 2024). A syndrome resulting from the acquired deficiency of cellular immunity caused by the human immunodeficiency virus (HIV). "Since PLWH exhibit an immune aging phenotype and increased incidence of non-AIDS NCDs with metabolic disorders, in this study we assessed changes in plasma levels of GDF-15 and metabolic proteins." (PMID 38895099, 2024). "Further mechanistic studies in elucidating the interrelationship between GDF-15 and each individual metabolic protein are clearly warranted to understand their role in the development and management of non-AIDS NCDs in PLWH on ART." (PMID 38895099, 2024). "A recent study reported elevated levels of the mitochondrial stress marker GDF-15 in PLWH that were associated with aging, HIV reservoir size, and increased risk of developing non-AIDS comorbidities." (PMID 38895099, 2024). "Previous data have shown that non-AIDS comorbidities in PLWH are known to be influenced by metabolic, inflammatory, and viral factors; thus we tested markers related to such aspects, including GDF-15, suPAR, FGF-21, GLP-2, CRP, anti-CMV IgGs, and anti-EBV IgGs." (PMID 36093162, 2022).
Anxiety (5 papers, 2017 to 2025). Intense feelings of nervousness, tension, or panic often arise in response to interpersonal stresses. "GDF15 emerges as a key stress-responsive biomarker that links peripheral metabolism with brainstem GDNF family receptor alpha-like (GFRAL)-mediated anxiety circuits." (PMID 40806735, 2025). "GDF15 has recently been identified as a stress-responsive biomarker that directly links peripheral metabolic status with central anxiety circuits through brainstem GDNF family receptor alpha-like (GFRAL) receptors." (PMID 40806735, 2025). "GDF15-GFRAL signaling plays a key role in stress-induced anxiety-like behaviors." (PMID 40806735, 2025). "In line with this, Mic-1/Gdf15 deficient mice regardless of sex displayed significantly less anxiety-related behaviours across tests." (PMID 28081177, 2017). "This suggests that GDF15 might be effective to induce stress and anxiety." (PMID 34831213, 2021). "GDF15 then acts on brainstem GFRAL receptors to regulate energy balance and anxiety-like behaviors." (PMID 40806735, 2025).
brain tumors (5 papers, 2016 to 2025). "Patients with hepatobiliary cancer exhibited the highest GDF-15 levels (median 6,233 ng/L; Q1-Q3: 3,285-9,861 ng/L), whereas patients with brain tumors had the lowest levels (median 858 ng/L; Q1-Q3: 522-1,150 ng/L)." (PMID 39967200, 2025). "In fact, brain tumor cells are continuously and repeatedly exposed to the GDF15-secreting ECs." (PMID 35280749, 2022). "Indeed, it has been shown that GDF15 exhibited higher expression levels in secondary and lower expression in primary brain tumors, while its role in brain tumor progression was found to be inconsistent acting in a cell type- and context-dependent manner." (PMID 31612114, 2019). "Furthermore, this study demonstrated the in vivo effect of GDF15 on brain tumor angiogenesis." (PMID 35280749, 2022).
Cerebral ischemia (5 papers, 2016 to 2026). Restriction of arterial blood supply to the brain associated with insufficient oxygenation to support the metabolic requirements of the tissue. "In the brains of rats and mice, where GDF-15 is physiologically expressed in the choroid plexus epithelium, cortical lesioning or cerebral ischemia has been shown to induce a significant increase of GDF-15 expression in the injured cortex." (PMID 31258506, 2019). "Other data have also shown the induction of GDF-15 mRNA expression in the ipsilateral hippocampus and parietal cortex 3 and 24 h after cerebral ischemia induced by middle cerebral artery occlusion in mice." (PMID 31258506, 2019). "It has been proposed that catecholamines, released during acute myocardial or cerebral ischemia, may remotely induce GDF15 secretion." (PMID 38839839, 2024). "The consequences of remotely-induced GDF15 upregulation in the heart by cerebral ischemia are unknown, but may reflect a new interaction between the brain and the heart during ischemic processes." (PMID 39008451, 2024).
chronic fatigue syndrome (5 papers, 2019 to 2023). "In this study, we aimed to assess the diagnostic performance of GDF-15 in patients with mitochondrial disease that presents only as fatigue and exercise intolerance and to distinguish them from those with chronic fatigue syndrome." (PMID 36983435, 2023). "This is an arousing aspect since it was shown that patients with chronic fatigue syndrome, which has been linked to LD, display higher GDF15 levels than healthy controls." (PMID 32375259, 2020). "Interestingly, GDF15 expression increased in dorsal spinal cord of rats with neuropathic pain and higher serum levels of this protein were detected among myalgic encephalomyelitis/chronic fatigue syndrome patients when compared with healthy subjects." (PMID 32582603, 2020).
congenital heart disease (5 papers, 2020 to 2025). A heart disease that is present at birth. "In one cross-sectional study of patients with congenital heart disease, children with congenital heart disease and a failure to thrive had significantly higher levels of GDF15 compared to their normal weight controls." (PMID 32310257, 2020).
endometrial cancer (5 papers, 2016 to 2022). Primary or metastatic malignant neoplasm involving the endometrium (mucous membrane that lines the endometrial cavity). "In this study, we validate that high level of plasma GDF-15 is associated with clinical characteristics depicting aggressive disease and poor survival in endometrial cancer." (PMID 30645608, 2019). "Importantly, we find that in patients with putative low risk based on preoperative histology (endometrioid grade 1 or 2), high level of GDF-15 predicts poor prognosis and is associated with aggressive features in endometrial cancer." (PMID 30645608, 2019). "A conference abstract in the European journal of Cancer reported that GDF15 promotes endometrial cancer metastasis by EMT." (PMID 34951691, 2022). "A conference abstract in the European journal of cancer reported that GDF15 promotes endometrial cancer metastasis by cellular invasion." (PMID 34951691, 2022). "As the plasma level of GDF-15 has been reported to be elevated in cancers compared to healthy controls, we investigated if plasma GDF-15 also is a marker for progression from hyperplasia to endometrial cancer." (PMID 30645608, 2019). "Plasma concentrations of GDF-15 were compared between 78 patients with endometrial hyperplasias and 235 patients with primary endometrial cancer." (PMID 30645608, 2019). "This suggests a promising role for GDF-15 in confirming preoperatively that some putative low-risk patients have an excellent prognosis, supporting the clinical value of plasma GDF-15 in endometrial cancer treatment." (PMID 30645608, 2019). "GDF-15 measured in plasma samples from 235 patients with endometrial cancer in relation to clinicopathological factors." (PMID 30645608, 2019). "When performing a more detailed analysis of endometrioid endometrial cancers only, we observed that the increase of GDF-15 occurs between grade 1 and grade 2 (p = 0.003)." (PMID 30645608, 2019). "In the present study we wanted to explore the applicability of GDF-15 in predicting endometrial carcinoma recurrence." (PMID 30645608, 2019). "Our results are in line with these findings and validate GDF-15 as a prognostic marker in endometrial carcinoma." (PMID 30645608, 2019). "For uterine sarcomas, elevated GDF-15 may aid in discriminating aggressive sarcomas from benign leiomyomas, whereas for endometrial cancer increased GDF-15 expression has been reported to predict lymph node metastases and poor survival." (PMID 30645608, 2019). "In addition, high GDF-15 indicated reduced recurrence-free survival (p<0.001) with 5-year recurrence-free survival rate of 61.2% compared to 89.3% in endometrial cancer." (PMID 30645608, 2019). "Measuring GDF-15 in plasma from patients with endometrial cancer may be helpful when selecting women who are likely to profit from adjuvant therapy after primary treatment." (PMID 30645608, 2019). "In addition, using an extensive panel of clinicopathological variables including survival, our aim was to validate GDF-15 as a prognostic marker in endometrial carcinoma and as a possible predictor of lymph node metastases." (PMID 30645608, 2019). "Several markers of survival among endometrial cancer (EC) patients have beenproposed, namely, the oncoprotein stathmin, RAF kinase inhibitor (RKIP),Cyclin A, GATA-binding protein 3 (GATA3), and growth and differentiationfactor-15 (GDF-15)." (PMID 35533253, 2022). "However, the use of disease-specific survival in our survival analyses and the identified association with both high grade and myometrial infiltration, which is independent of comorbidity and high age, support that GDF-15 specifically detects aggressive endometrial cancer in our cohort." (PMID 30645608, 2019).
esophageal cancer (5 papers, 2020 to 2026). A primary or metastatic malignant neoplasm involving the esophagus. "GDF15, belonging to the TGF-β superfamily, has been reported to serve as a tumor suppressor in several cancers, including esophageal carcinoma 31-34." (PMID 35069911, 2022).
gestational diabetes (5 papers, 2023 to 2026). Carbohydrate intolerance first diagnosed during pregnancy. "In this study, the prevalence of GDM was significantly increased in GDF-15 rs4808793 allele polymorphism (C) carriers; this finding is consistent with the results of a previous study showing that high GDF-15 levels in late pregnancy are associated with gestational diabetes." (PMID 39666683, 2024). "Previous meta‐analyses showed GDF15's increases up to d = 0.48 in gestational diabetes mellitus (Y.‐C." (PMID 40708105, 2026). "The aim of this pilot study was to evaluate the relationship between a circulating concentration of GDF-15 and metabolic/inflammatory parameters, as well as with adverse perinatal outcomes in patients with gestational diabetes mellitus (GDM)." (PMID 40283592, 2025).